RUNX1 (RUNX family transcription factor 1)
Diseases named in the same sentence as RUNX1 in open-access papers (continued):
Sharing a sentence is not in itself a finding about the gene and the disease.
myelodysplastic syndrome (continued). "A recent research has shown that Stag2 and Runx1 play an important role in regulating chromatin looping and transcription in hematopoiesis, and cohesin-Runx1 deficiency can induce myeloid-skewed expansion of HPSCs and myelodysplastic syndromes (MDS)." (PMID 33928020, 2021). "Germline RUNX1 mutations are found in FPD/AML characterized by thrombocytopaenia, and a 35% life‐time risk of developing myelodysplastic syndrome (MDS) and/or AML." (PMID 27997762, 2017). "Mutations of RUNX1 are reported in approximately 10–16% of AML patients and 12–24% of myelodysplastic syndrome (MDS) patients." (PMID 28933735, 2017). "Moreover, BMI1 overexpression is frequently observed in myelodysplastic syndrome (MDS) patients harboring RUNX1 mutations." (PMID 24348510, 2013). "RUNX1 mutations are identified in 10% of patients with AML and myelodysplastic syndrome (MDS)." (PMID 40225162, 2023). "Individuals with familial myelodysplastic syndromes (MDS), which is associated with mutations in the RUNX1 gene, have a median AML incidence of 35% in carriers, but this varies greatly between families, as does the age of onset, which ranges from childhood to old age even within the same family." (PMID 25056697, 2014). "In contrast, the TET2, FLT3, RUNX1, BCOR and spliceosome mutations were more common in the IDO1-high group, which were commonly enriched in myelodysplastic syndrome (MDS)-transformed AML." (PMID 40234305, 2025). "RUNX1-FPDMM is a challenging disease due to its associated increased risk for hematologic malignancies, mainly myelodysplastic syndrome (MDS) or AML." (PMID 41458504, 2025). "In addition, RUNX1 mutations are also commonly found in a number of pre-leukemic diseases, such as myelodysplastic syndrome (MDS) and family platelet disorders (FPD), with predisposition to AML, showing RUNX1 mutation is an early event and the driving force to the cancer." (PMID 31048839, 2019). "Inherited mutations in ANKRD26, which is transcriptionally regulated by RUNX1 lead to a similar clinical phenotype, in which thrombocytopenia is often associated with AML and in some cases, with chronic myelogenous leukemia, chronic lymphocytic leukemia and myelodysplastic syndrome." (PMID 26102509, 2015). "The RUNX1 (AML1) mutant (D171N) occurs in 40% of myelodysplastic syndromes (MDS), with 30%–40% undergoing transformation to AML." (PMID 26384344, 2015). "More recent large-scale sequencing studies have uncovered the occurrence of RUNX1 mutations in a significant percentage of AML and myelodysplastic syndrome (MDS)." (PMID 23344057, 2013). "LEN, which has demonstrated clinical efficacy in multiple myeloma and striking activity in myelodysplastic syndrome (MDS), can upregulate RUNX1 in hematopoietic stem and progenitor cells." (PMID 38916960, 2024). "To analyze specific gene expression patterns of ETV6::RUNX1‐translocated preleukemia in a model without additional secondary alterations, we generated monoclonal hiPSC lines derived from two donors: HW8 and ChiPSC12." (PMID 40177616, 2025). "Myeloid gene mutations: RUNX1 44.14%, U2AF1 40.74%, PHF6 (c.663_668clclims13) 6.3%, PHF6 (c.725G>A) 73.26%; myelodysplastic syndrome (MDS)-FISH were all negative." (PMID 38457569, 2024). "RUNX1 mutational status did not significantly correlate with WBC count, hemoglobin, or peripheral blood and bone marrow blasts, or history of prior myelodysplastic syndrome or myeloproliferative neoplasms (MDS/MPN) or therapy-related AML (t-AML)." (PMID 28933735, 2017).
myeloid neoplasm (81 papers, 2008 to 2026). Proliferation of myeloid cells originating from a primitive stem cell. "Germline mutations in RUNX1 are associated with the leukemia predisposition syndrome Familial Platelet Disorder with Associated Myeloid Malignancies." (PMID 41214140, 2026). "It is estimated that ∼40% of individuals diagnosed with FPD/AML will develop a myeloid neoplasm, since germline RUNX1 variants alone are insufficient to induce AML, and that second-hit mutational events are necessary." (PMID 40427601, 2025). "The genome-first UK BioBank cohort study reported deleterious germline RUNX1 alleles increase the risk of HMs in general (odds ratio 66) and myeloid malignancies (odds ratio 210) in particular (p ≤ 0.001)." (PMID 40563019, 2025). "Germline RUNX1 mutations cause Familial platelet disorder with associated myeloid malignancies (FPDMM), which is characterized by an increased risk of developing hematologic malignancies." (PMID 40805145, 2025). "Somatic variants in the RUNX1 gene are one of the most frequently identified variants and have been identified in patients with various myeloid malignancies, including MDS, MPN, and AML." (PMID 38203823, 2024). "ASXL1mt in myeloid neoplasms were considered to be ubiquitously accompanied by mutations of RUNX1, SRSF2, STAG2, NRAS, or IDH2, in addition to wild‐type NPM1 and FLT3,14, 21, 22, 28 which was aligned with the mutation profile in our cohort." (PMID 38146893, 2023). "RUNX1 is a critical transcription factor for hematopoiesis; RUNX1 mutation is recurrently detected and is a poor prognostic marker in myeloid malignancies." (PMID 36185231, 2022). "Recent studies have revealed that somatic mutations are detected in approximately 30% of AA patients, and mutations in several genes such as DNMT3A, ASXL1, and RUNX1 are associated with secondary myeloid malignancies." (PMID 36467821, 2022). "In 1999, germline RUNX1 mutation was identified, for the first time, as the genetic background of familial platelet disorder with predisposition to myeloid malignancy (FPD-MM)." (PMID 36185231, 2022). "RUNX1 truncating and frameshift mutations have been reported in myeloid neoplasms, supporting its role as a tumor suppressor." (PMID 35799207, 2022). "Recently, evidence emerged that besides T-ALL also lymphoid malignancies of B-cell origin are part of the phenotypic spectrum, even though RUNX1 germline variants are primarily associated with myeloid malignancies." (PMID 35884491, 2022). "A subset of patients with familial thrombocytopenia are at increased risk of developing myeloid neoplasms during their life time, particularly those with germline autosomal dominant mutations in the RUNX1, ANKRD26, and ETV6 genes." (PMID 33802366, 2021). "Germline RUNX1 mutations are reported in inherited forms of platelet disorders with a predisposition to myeloid malignancies." (PMID 34830822, 2021). "In patients with germline RUNX1 mutations, a second allele often acquires somatic mutation at the time of progression to an overt myeloid neoplasm, likely as a result of an impaired DNA repair pathway and an increased mutagenicity." (PMID 35054439, 2021). "Other co-mutations often seen in myeloid neoplasms with germline RUNX1 are in DNMT3A, FLT3, GATA2, PHF6 (PHD finger protein 6), BCOR (BCL6 Corepressor), WT1, and TET2." (PMID 35054439, 2021). "The overall morphological and molecular findings exclude ET and suggest an alternative diagnosis of RUNX1-mutated myeloid neoplasm with thrombocytosis." (PMID 34830822, 2021). "Myeloid neoplasms with germline RUNX1 mutations result from monoallelic RUNX1 mutations occurring all along this gene, including missense, nonsense, frameshift, insertions, deletions, and, a recently reported, disrupting congenital translocation." (PMID 28955657, 2017).
myeloid neoplasm (continued). "Monoallelic RUNX1 mutations carriers show a heterogeneous range of clinical manifestations: from moderate thrombocytopenia, bleeding, or myeloid neoplasm with frequent strong anticipation, to asymptomatic family members." (PMID 28955657, 2017). "Management of patients with myeloid neoplasms and germline RUNX1 mutations depends on clinical presentation." (PMID 28955657, 2017). "Haploinsufficiency of RUNX1 causes familial platelet disorder with predisposition to myeloid malignancies (FPD/MM)." (PMID 26745853, 2016). "Runt-Related Transcription Factor is a tumor suppressor in myeloid neoplasms, and mutations in RUNX1 are previously associated with unfavourable outcome in CN-AMLs." (PMID 25734857, 2015). "In 1999 RUNX1 germline mutations were linked to a familial platelet disorder with associated myeloid malignancy, a rare autosomal dominant disease characterized by thrombocytopenia and a predisposition to myeloid neoplasms." (PMID 41464583, 2025). "Notably, germline loss-of-function mutations in DDX41 and RUNX1 cause myeloid neoplasm predisposition." (PMID 36814285, 2023). "For example, the RUNX1 gene is considered a tumor suppressor gene in myeloid neoplasm and was recently implicated in gastrointestinal tumorigenesis, as a novel tumor-suppressor gene, which maintains the balance between the intestinal stem/progenitor cell population and epithelial differentiation." (PMID 27481518, 2016). "Therefore, AML with somatic RUNX1 variants is considered a biologically distinct AML subtype associated with poor outcomes in the 2016 revision of the World Health Organization (WHO) classification of myeloid neoplasms and acute leukemia." (PMID 35884491, 2022). "Germline testing of DNA from cultured skin fibroblasts reveled a deletion of exons 5-6 of the RUNX1 gene, classified as P by ACMG Myeloid Malignancy Variant Curation Expert Panel (MM-VCEP) criteria." (PMID 40148527, 2025). "ETNK1 mutation is an early event in myeloid neoplasms, often co-occurring with ASXL1, TET2, EZH2, RUNX1, and SRSF2 mutations." (PMID 40074445, 2025). "All patients found to have an HHMS were diagnosed with a myeloid neoplasm under age 50, except for the patients with RUNX1 and DDX41 PVs, who were diagnosed in their 60s." (PMID 40936482, 2025). "Some investigations reported the co-occurrence of ASXL1 mutations with EZH2, IDH1/2, RUNX1, and TET2 in myeloid malignancies." (PMID 38807730, 2024). "To understand the role of functional immune system in AML progression, we have used several mouse myeloid tumor models driven by MLL-AF9, RUNX1-ETO9a, ASXL1/RUNX1 mutations and ASXL1/SETBP1 mutations." (PMID 38129572, 2023). "Of note, ARCH is characterized by the presence of somatic mutations in genes that are also frequently mutated in SM (e.g., ASXL1, DNMT3A, EZH2, RUNX1, SF3B1, SRSF2 and TET2) and other myeloid neoplasms." (PMID 35626091, 2022). "In the list of germline mutations with predisposition to myeloid neoplasms, many encode known master transcription factors, such as CEBPA, RUNX1, and GATA2." (PMID 35054439, 2021). "Mutations in transcription factors such as CEBPA, RUNX1, and GATA2 can be seen in myeloid neoplasms, both de novo or with germline predisposition." (PMID 35054439, 2021).
myeloid neoplasm (continued). "STAG2 mutations are almost always accompanied by other driver mutations, such as in RUNX1, SRSF2, and ASXL1, but how cohesin mutations induce myeloid neoplasms in conjunction with other driver mutations remains to be determined." (PMID 33799787, 2021). "Each SF is also associated with a distinct pattern of mutations in other genes commonly detected in myeloid malignancies, as in the case of SRSF2 mutations with TET2 mutations in CMML and with RUNX1, IDH2, and ASXL1 mutations in AML." (PMID 31766606, 2019). "Inactivating RUNX1 mutations have been described in myeloid neoplasms including MDS and cytogenetically normal AML, thus RUNX1 can be considered a tumor suppressor in these malignancies." (PMID 25914884, 2015). "This knowledge may have prompted the family to seek specialty care sooner and a hematologist may have recognized the months-long prodrome sometime seen with germline RUNX1-related myeloid malignancies." (PMID 40563019, 2025). "In patients with myeloid neoplasms and germline predisposition without potential organ dysfunction (i.e., patients with germline mutation in RUNX1, DDX41, CEBPA and so on), no specific complication after HSCT has been reported till date." (PMID 36185231, 2022). "Of note, ASXL1 mutations are frequently seen with other gene alterations, such as with EZH2 IDH1/2, RUNX1, and TET2, most of which are adverse prognostic factors themselves in myeloid neoplasms, potentially explaining why ASXL1 mutations are associated with poor prognosis in many cases." (PMID 34947882, 2021). "Moreover, recent studies have shown the interaction of RUNX1 with other frequently co-mutated drivers, such as STAG2 and ASXL1, thus promoting the advancement of myeloid neoplasms." (PMID 33799787, 2021). "Other genes commonly mutated in myeloid neoplasms, such as FLT3 (fms like tyrosine kinase 3), DNMT3A (DNA Methyltransferase 3 Alpha), IDH1/2 (Isocitrate Dehydrogenase (NADP(+)) 1/2), NPM1 (Nucleophosmin 1), and RUNX1, are rare and almost mutually exclusive." (PMID 35054439, 2021). "Of note, in 2016 the World Health Organization classification included myeloid malignancies arising from germline mutations in ANKRD26, RUNX1, and ETV6 into a new category defined as “Myeloid neoplasms with germline predisposition and pre-existing platelet disorders”." (PMID 33802366, 2021). "However, there are marked differences in cancer predisposition: the ANKRD26 variant predisposes to myeloid malignancies, ETV6 predominantly predisposes to B-cell ALL, and RUNX1 is associated with myeloid malignancies, and, to a lesser extent, predisposes to T-cell ALL." (PMID 38203823, 2024). "While RUNX1 mutations are considered rather rare in BPDCN we observed eleven cases, however, most of these (nine out of eleven) where these mutations were subclonal events and some cases even exhibited syn- and/or metachronous myeloid neoplasms other than BPDCN." (PMID 38600314, 2024). "The ICC has recognized RUNX1 mutations as myelodysplasia-related in AML, and therefore, cases of myeloid neoplasms with ≥10–19% blasts in the bone marrow are defined as MDS/AML, while cases with ≥20% blasts are defined as AML with myelodysplasia-related gene mutations (RUNX1)." (PMID 37510328, 2023). "For example, microhomology-mediated recurrent deletions of CALR, ASXL1, and SRSF2 and non-recurrent deletions in TET2, DNMT3a, CEBPA, and RUNX1 have been reported in myeloid neoplasms." (PMID 36011278, 2022). "Moreover, they found mutations in known-CHIP-associated genes, including DNMT3A and TET2, in 22% of preleukemic RUNX1-FPD patients and 40% of patients with myeloid malignancy, which is more frequently than within the general population." (PMID 35884491, 2022). "Germline mutations in RUNX1 lacking the C-terminus, which would disrupt the interaction with PTBP1, have been reported in patients with Familial Platelet Disorder with associated Myeloid Malignancies." (PMID 41214140, 2026).
myeloid neoplasm (continued). "Interestingly, genes commonly mutated in AML and other myeloid neoplasms, such as FLT3, NPM1, KIT, RUNX1, and DNMT3A, were absent in our cohort." (PMID 40526100, 2025).
Thrombocytopenia (63 papers, 2011 to 2025). A reduction in the number of circulating thrombocytes. "Cascade testing for the family was performed, and the RUNX1 variant was found to segregate with individuals in the family who exhibited thrombocytopenia, abnormal bleeding, and bruising." (PMID 40148527, 2025). "The increased bleeding tendency observed in individuals carrying RUNX1 variants—often more pronounced than in other forms of mild thrombocytopenia—can be attributed to impaired platelet function, most clearly demonstrated by LTA." (PMID 41458504, 2025). "FPD‐MM families, related to RUNX1 mutations, regroup cases of thrombocytopenia and myeloid malignancies, with autosomal dominant transmission." (PMID 36819173, 2023). "Variants of ANKRD26 and of transcription factors ETV6 and RUNX1, which are associated with autosomal dominant (AD) inherited disorders, represent almost one-quarter of inherited thrombocytopenia cases." (PMID 36430862, 2022). "Once a diagnosis of inherited thrombocytopenia with germline mutation in RUNX1, ANKRD26, or ETV6 is established, close and long-term surveillance is mandatory given the lifelong increased risk of developing hematologic malignancies." (PMID 33802366, 2021). "While several studies have identified a myriad of germline RUNX1 mutations implicated in this disorder, second-hit mutational events are necessary for patients with hereditary thrombocytopenia to develop full-blown AML." (PMID 29780592, 2018). "The RUNX1 or ANKRD26 mutations should be suspected among patients with thrombocytopenia with a family history of bleeding and/or MDS/AML." (PMID 28955657, 2017). "Familial platelet disorder with predisposition to acute myeloid leukaemia (FPD/AML) is characterized by germline RUNX1 mutations, thrombocytopaenia, platelet dysfunction and a risk of developing acute myeloid and in rare cases lymphoid T leukaemia." (PMID 27997762, 2017). "PM21 deletions encompassing RUNX1 and RUNX1 haplodeficiency are also commonly associated with thrombocytopenia, which is consistent with our haematology analysis." (PMID 26035870, 2015). "Runx1 deficient adult mice also showed impaired lymphoid and megakaryocytic differentiation, a reduced number of lymphoid progenitors, and thrombocytopenia." (PMID 23344057, 2013). "Upon loss of Runx1 the program is abrogated leading to aberrant megakaryocytic maturation, sustained proliferation of FL-MKRunx1−/− and thrombocytopenia in Runx1F/F/Pf4-Cre mice." (PMID 23717578, 2013). "RUNX1 encodes a transcription factor that prevents DNA from getting degraded, which vital for embryonic hematopoiesis, adult megakaryocyte, and platelet development, with most mutations leading to thrombocytopenia." (PMID 39355256, 2024). "Moreover, it was previously shown in mice and humans that mutations in Nfe2, Fli1 and Runx1 cause thrombocytopenia, and that promoter occupancies with NFe2, Fli1 and Runx1 correlated with terminal MK differentiation." (PMID 38067194, 2023). "The RUNX1 variant p.E223G was identified in a 22-year-old woman with thrombocytopenia." (PMID 40225162, 2023). "In addition, the transactivation assays were applied to investigate 11 RUNX1 variants detected in patients with thrombocytopenia, MDS, AML, or as secondary finding to independently validate our assays." (PMID 34633564, 2021). "Insofar management for thrombocytopenias associated with RUNX1, ANKRD26, or ETV6 mutations are concerned, a cytogenetic bone marrow examination is recommende at the time of diagnosis, particularly if the mutations have already been reported and have proven pathogenicity." (PMID 33926054, 2021). "Besides, alteration in MYH10 distribution has been reported as a sign of thrombocytopenia due to FLI1 or RUNX1 mutations." (PMID 32079152, 2020).